VHL (von Hippel-Lindau tumor suppressor)
Diseases named in the same sentence as VHL in open-access papers (continued):
Sharing a sentence is not in itself a finding about the gene and the disease.
renal carcinoma (282 papers, 2004 to 2026). A carcinoma arising from the epithelium of the renal parenchyma or the renal pelvis. "Previous studies were conducted in VHL-deficient renal carcinoma cells, which resulted in the stabilization of HIF proteins in this cell line." (PMID 41511382, 2026). "This also explains perturbation in such cell cycle regulators as VHL, which is missing in 80% of renal cancers, or arresting cell cycle with DTB, would cause different R5P changes in our previous and current studies." (PMID 41020695, 2025). "To further explore ISG expression in VHL-deficient renal cancer, we analysed the single cell transcriptional profiles of treatment-naive renal tumours from 12 patients, who underwent surgical resection." (PMID 39282259, 2024). "In the context of renal cancer, the loss of VHL triggers the constitutive activation of HIF transcriptional complexes." (PMID 39011666, 2024). "Stabilization of HIF in mammals through loss of the E3 ubiquitin ligase von Hippel-Lindau (VHL) protein led to a disease characterized by renal carcinomas, whereas in C. elegans, loss of vhl-1, improved proteostasis and increased lifespan." (PMID 39636438, 2024). "BCAA catabolism in renal cancer cells is linked to the glutamate–glutamine axis, transcriptional sensitivity to VHL restoration, epigenetic modification, enhanced tumour immunity, and ferroptosis." (PMID 38136342, 2023). "The aim of this study was to examine the consequences of VHL-C162F mutation on morphology, proliferation, ability to form colony and healing ability of renal carcinoma cells." (PMID 38201462, 2023). "In VHL-deficient renal cancer cells, BCAA catabolism represents an indirect source of nitrogen for nucleotide and non-essential amino acid biosynthesis at all stages of tumour evolution." (PMID 38136342, 2023). "Based on an analysis of 79 genes associated with renal cancer, we found that VHL, PBRM1, BAP1, SETD2, and TSC1 mutation rates were higher in all RCCs at 51%, 35%, 16%, 15%, and 13%, respectively." (PMID 37427096, 2023). "On the other hand, overexpression of VHL induced downregulation of SETDB1 in VHL-deficient renal carcinoma cells." (PMID 37850636, 2023). "As reported in our review, the most common somatic gene mutations in renal cancer are related to VHL, PBRM1, BAP1, and SETD2, although a relatively small number of other mutated genes are reported to be involved in kidney cancer." (PMID 36902045, 2023). "The majority of renal carcinomas are sporadic, and numerous are the genetic alterations involved; in particular, the most important mutations involve the tumor-suppressor VHL, observed in about 80% of ccRCC." (PMID 36212468, 2022). "Those with VHL mutations also have an increased risk of renal carcinomas and hemangioblastomas; thus, an abdominal MRI every 12 months and a central nervous system MRI every 24–36 months should be considered." (PMID 35205664, 2022). "VHL is a tumor suppressor gene, and mutations of VHL are closely related to the occurrence of renal cancer." (PMID 36267974, 2022). "Because renal carcinoma is a leading cause of death for patients with VHL disease, we chose to characterize the roles of VHL mutants in the VHL-defective cell model 786-O in subsequent analyses." (PMID 35505422, 2022). "Here we revealed that PVT1 protected HIF2α from polyubiquitination and subsequent proteasomal degradation in VHL-deficient renal cancer cells." (PMID 34321604, 2021). "Here, we describe that as a single agent, CX-4945 moderately induced cell death in VHL-deficient renal cancer cells but unexpectedly, triggered a strong ATM upregulation, providing a potential link between CK2 and ATM pro-survival pathways." (PMID 33540838, 2021). "It should be noted that the role of VHL E3 ligases have been recently linked to TGFβ signaling in a renal cancer model." (PMID 33418880, 2021). "Inactivating mutation of the von Hippel-Lindau (VHL) gene is a hallmark of renal carcinoma cells which is detectable in the majority of RCC patients." (PMID 34670568, 2021).
renal carcinoma (continued). "Combined inhibition of CK2 and ATM eliminated VHL-deficient renal carcinoma cells by increasing NOX4-mediated ROS production." (PMID 33540838, 2021). "Chemo-genetic screens revealed CK2 and ATM kinases as synthetic lethal targets in VHL-deficient renal carcinoma cells." (PMID 33540838, 2021). "The gene encoding CA XII, CA12, is a target of hypoxia-inducible factor 1 (HIF-1), and a common feature of many renal carcinomas is mutations in the von Hippel-Lindau (VHL) tumor suppressor gene, a regulator of HIF-1." (PMID 35582034, 2021). "In fact, a recent study examined the effects of VHL reconstitution on CHCHD4 function in renal carcinoma cells (RCC), since RCC exhibit loss of VHL function, and consequently HIF is constitutively activated." (PMID 33599699, 2021). "Here, we combined genetic and chemical screens to systematically search for lethal interaction in VHL-deficient renal cancer cells." (PMID 33540838, 2021). "Among the effective combinations identified from this screen, we found that a novel combination, pairing the CK2 inhibitor CX-4945 with the ATM inhibitor KU-60019, dramatically enhanced cell death in VHL-deficient renal carcinoma cells." (PMID 33540838, 2021). "VHL is commonly mutated in renal cancer, and the subsequent loss of VHL-dependent ubiquitin ligase activity contributes to tumor growth and metastasis." (PMID 34831344, 2021). "Previous studies have shown that loss or mutation of Von Hippel-Lindau tumor suppressor (VHL) is a critical driver of ccRCC and is believed to occur at an early stage in renal cancer." (PMID 33575207, 2020). "Studies based on the analysis of early renal cancers derived from nephrectomies performed in VHL disease patients provided evidence that biallelic inactivation of VHL is observed in preneoplastic renal lesions, in association with HIF activation." (PMID 32751108, 2020). "We noted that HIF-1α, which is highly expressed in VHL-mutated renal cancer cells, acts as a downstream effector of QKI." (PMID 32047543, 2020). "It is important to note that in Von Hippel-Lindau disease only one of the two VHL alleles carries a germline mutation; therefore, in these patients, the inactivation of the second allele is one of the first events during renal cancer development." (PMID 32751108, 2020). "We measured expression levels of both genes in VHL-deficient (high levels of HIF) and VHL–re-expressing (low levels of HIF) renal cancer cell lines (RCC4 and RCC10) exposed to control or DMOG conditions." (PMID 31690629, 2020). "The hypoxia response is the most critical to incidence of renal carcinoma, which is frequently associated with mutations of Von Hippel–Lindau (VHL) gene." (PMID 31114448, 2019). "In contrast, expression of VHL in 786-O cells, a VHL-deficient renal carcinoma cell line, restored TD-158–induced CRBN degradation." (PMID 31873151, 2019). "HIF-1 is required for tumorigenesis in VHL-deficient renal carcinoma cells, and these effects are mediated by HIF-1 via inhibiting C-MYC activity, which determines the transcription of the gene encoding the coactivator PGC-1b." (PMID 31711497, 2019). "Here we shed light on the previously unrecognized molecular mechanism underlying aberrant activation of hypoxia response in VHL-intact renal carcinoma and our data uncovered an alternative pathway through which hypoxia response was activated." (PMID 31114448, 2019). "VHL, a protein involved in proteasomal degradation of HIFs, is frequently mutated in renal cancers and consequently, this results in HIF accumulation leading to the induction of pro-angiogenic factors and malignant progression." (PMID 31014368, 2019). "Our study unraveled a novel mechanism underlying hypoxic context in VHL-proficient renal cancer, which held potential promise for diagnostic and therapeutic exploitations." (PMID 31114448, 2019).
renal carcinoma (continued). "Our results expand the current knowledge of DNA repair regulation in cancer and identify a potential therapeutic target in VHL-deficient renal carcinoma." (PMID 29435132, 2018). "We compared DNA methylation between renal cancer cell lines with mutated VHL (A498, 786-O) and those with wild-type VHL (ACHN, Caki-1)." (PMID 30006568, 2018). "Previous evidence demonstrated that restoration of wild type VHL in human renal cancer cells decreased their NK susceptibility while VHL mutations increased resistance to NK-mediated lysis through EPAS1/HIF-2α stabilization." (PMID 30514329, 2018). "Taken together, we demonstrate that loss of VHL dramatically impacts the DNA methylation landscape of renal cancer cells while in contrast there are relatively few changes to 5MeC in hypoxia." (PMID 29463811, 2018). "We have further established that this decrease in HR gene expression is associated with reduced repair of DNA double-strand breaks by HR and consequent sensitivity to PARP inhibitors in VHL-deficient renal carcinoma cells." (PMID 29435132, 2018). "Previous evidence demonstrated that restoration of wild type VHL in human renal cancer cells decreased in vitro NK susceptibility." (PMID 30514329, 2018). "In our study blood derived from patients carrying RCC-VHL-MUT tumors display better NK susceptibility toward human renal cancer cells VHL-MUT suggesting an improvement in the innate immune response toward RCC." (PMID 30514329, 2018). "Reintroduction of wild-type VHL into VHL-deficient renal carcinoma cells suppresses tumor formation, establishing its role as a tumor suppressor." (PMID 29435132, 2018). "Our experiments were performed with VHL-deficient renal carcinoma cell line RCC4 and RCC4 VHL line with reintroduced wild-type VHL." (PMID 29560117, 2018). "Our findings of decreased HR gene expression, impaired DNA double-strand break repair capacity, and sensitivity to PARP inhibitors indicate that VHL-deficient renal carcinoma shares some features with BRCAness tumors." (PMID 29435132, 2018). "We also noted the reported sensitivity of VHL-deficient renal cancer cells to glutamine starvation, but remarkably the cells were still able to store lipids in droplets." (PMID 29176561, 2017). "Abnormality of the VHL has been reported to be linked to the development of renal carcinomas and hemangioblastomas." (PMID 28009993, 2017). "Reductive carboxylation has been associated with the loss of the von Hippel-Lindau tumor suppressor (VHL) in renal cancer cell lines." (PMID 28806730, 2017). "Reductive carboxylation has been observed in renal cancers with VHL mutations under normal oxygen conditions." (PMID 28806730, 2017). "We also show that analysis of mutations in VHL using our workflow provides valuable insights into the effects of mutations, and their links to the risk of developing renal carcinoma." (PMID 26797105, 2016). "In renal carcinoma, loss of VHL can lead to sustained up-regulation of both HIF-1α and HIF-2α isoforms in some tumors or only HIF-2α in other tumors, but not solely HIF-1α." (PMID 25729330, 2015). "The distinct contributions of HIF-1α versus HIF-2α toward apoptosis were then investigated using VHL-deficient renal carcinoma cell lines and manipulation of HIF-1α and HIF-2α expression." (PMID 25729330, 2015). "The expression of LC3B supports tumor formation and progression in renal cancer cells with VHL loss of function, whilst the expression of LC3C shows tumor suppressor activity." (PMID 28326269, 2015). "Inactivation of HIF can inhibit tumorigenesis among VHL-deficient renal carcinoma cells in xenograft models." (PMID 25373733, 2014). "Inherited and sporadic forms of ccRCC account for 85% of renal cancers and loss of the VHL tumour suppressor gene is involved in 70% of sporadic ccRCC." (PMID 23785518, 2013). "Here we show for the first time that VHL loss-of-function results in dramatic upregulation of NMU expression in renal cancer cells." (PMID 21791076, 2011).
renal carcinoma (continued). "Mutation or silencing of VHL accounts for >80% of all renal carcinomas, the most common form of kidney cancer." (PMID 20461086, 2010). "The effect of mTOR inhibitors on angiogenesis is likely to have an important function in renal carcinoma, a highly vascularised tumour associated with a VHL-driven angiogenesis." (PMID 18797463, 2008). "In renal cancer, loss-of-function mutations of VHL can cause HIF1α stabilisation, thereby inducing VEGF and PDGF overexpression and sustained tumour angiogenesis." (PMID 18797463, 2008). "In either case, it is likely that the loss of VHL-mediated differentiation synergizes with the effects of high HIF-α levels to lead to the development of renal carcinomas." (PMID 17598890, 2007). "A recent study has shown that VHL deficiency is one of the factors responsible for downregulation of the biogenesis of OXPHOS complexes in renal carcinoma." (PMID 16404428, 2006). "Tumour growth factor alpha, found to be upregulated by VHL mutation and hypoxia in this screen, has recently been shown to have a key role in growth of renal cancers." (PMID 15026807, 2004). "Most tumor-associated VHL mutants, when transfected into VHL-defective renal carcinoma cells, are defective in both complementing HIF dysregulation and fibronectin binding." (PMID 15361934, 2004). "These abnormalities can be corrected by transfection of renal carcinoma cells with wild-type vhl, indicating that they are attributable, either directly or indirectly, to VHL loss of function." (PMID 15361934, 2004). "HIF-1α is essential for tumorigenesis in VHL-deficient renal carcinoma cells." (PMID 40011447, 2025). "We found that classic renal cancer–related genes such as VHL, PBRM1, TTN, and SETD2 had higher mutation frequencies in the TCGA-KIRC cohort, with PBRM1 having a higher mutation rate in XPS1 compared to XPS2 (43% vs. 37%), while mTOR had a lower mutation rate in XPS1 compared to XPS2 (6% vs. 10%)." (PMID 39882192, 2025). "Analyzes how enhanced histone lactylation caused by inactive von Hippel-Lindau (VHL) may accelerate the development of renal cancer by activating the PDGFRβ signal." (PMID 39968078, 2025). "GPX4 and glutaminase inhibitors can inhibit pyrimidine synthesis and increase ROS levels in VHL-deficient renal carcinoma cells, and the PARP inhibitor olaparib and glutaminase inhibitors can synergistically inhibit the growth of these cells in vivo and in vitro." (PMID 39399506, 2024). "Patients with renal cancer had high prevalence of somatic variants in VHL gene (21.4%)." (PMID 39277826, 2024). "However, VHL mutations have also been described in several other subtypes of renal cancer; for instance, tubulocystic RCC (TC-RCC) (17%), papillary RCC (papRCC) (1.1%), chrRCC (1.5%), and FH-deficient RCC (1.8%)." (PMID 37999735, 2024). "Interestingly, in the majority of cases for the most common renal cancer subtype (ccRCC), the tumour suppressor gene Von Hippel-Lindau (VHL) is altered or inactivated, causing a loss of VHL." (PMID 37046847, 2023). "As another member of the JADE family JADE1 has been linked to renal cancer pathogenesis through a VHL-mutation-dependent mechanism, we next sought to determine if JADE2 mRNA was also associated with mutation of key oncogenic driver mutations in NSCLC such as KRAS or ALK." (PMID 37761019, 2023). "However, our results conclude that rs1642742 and rs779805 in the VHL gene are associated with increased tumor size, which is the most important prognostic indicator of renal cancer." (PMID 36835190, 2023).
renal carcinoma (continued). "However, our results conclude that rs1642742 and rs779805 in the VHL tumor suppressor gene are associated with increased tumor size, which is the most important prognostic indicator of renal cancer." (PMID 36835190, 2023). "As the tumor suppressor, VHL is highly frequently mutated in renal carcinomas." (PMID 37833251, 2023). "Furthermore, the CPGs DROSHA and VHL, with putative P/LP variants, are known to be associated with renal cancer." (PMID 35495172, 2022). "The inactivation of VHL leads to the structural activation of VEGF and PDGF, which can target downstream glutamine transporter SLC1A5, promotes the metabolic reprogramming of VHL deficient renal cancer cells, selectively reduces the growth and survival of VHL deficient renal cancer cells." (PMID 35022030, 2022). "To further address the clinical relevance of VHL mutations especially in human renal cancers, we performed an integrated analysis of HIF2α ChIP-seq data and VHL mutation-affected gene expression profiles, thereby identifying 11 genes directly bound by HIF2α and differentially altered by VHL-S65P." (PMID 35505422, 2022). "Collectively, these experiments suggest that HIF-2α-dependent vulnerability to combined inhibition of ATM and CK2 in VHL-deficient renal carcinoma cells may rely on a functional CK2–HIF-2α interaction." (PMID 33540838, 2021). "The aim of this study was to examine whether the VHL-R167Q mutation, which is associated with a high risk of developing ccRCC (type 2B VHL disease), could impact the plasticity of renal carcinoma cells." (PMID 34359798, 2021). "Importantly, our findings reveal a selective killing of VHL-deficient renal carcinoma cells and provide a rationale for a mechanism-based use of combined CK2/ATM inhibitors for improved patient care in metastatic VHL-ccRCC." (PMID 33540838, 2021). "Thus, our chemo-genetic screens revealed a vulnerability of VHL-deficient renal carcinoma cells to combined inhibition of CK2 and ATM kinases." (PMID 33540838, 2021). "Activation of the HIF pathway is a common final aspect of many cancers arising from a variety of events, including intratumoral hypoxia, signaling molecules (reactive oxygen species, cytokines, and growth factors) and oncogenic transformation (e.g., VHL loss of function in renal carcinoma)." (PMID 33499237, 2021). "Thus, HIF-2α acts as a mediator that potentiates CK2 and ATM inhibition to induce cytotoxicity in VHL-deficient renal carcinoma cells." (PMID 33540838, 2021). "Von Hipple Lindau disease (VHL) is an autosomal dominant syndrome caused by a mutation of the VHL tumor suppressor gene, inducing various benign and malignant tumors of the central nervous system, renal carcinomas or cysts, pheochromocytomas, epididymal cystadenoma and pancreatic tumors and cysts." (PMID 34885063, 2021). "Since different VHL status in renal carcinoma cells have been shown to affect their drug sensitivity in hypoxic conditions, we stably reintroduced VHL into 786-O VHL-deficient cells and evaluated their sensitivity to the CK2 and ATM inhibitors under low oxygen concentration (1.5%) (Figure 1C1,C2)." (PMID 33540838, 2021). "Thus, the loss of the short arm of chromosome 3, a frequent event in renal cancer, leads to the loss of VHL, but also BAP1, PBRM1 and SETD2 and, therefore, the loss of important tumor suppressor genes." (PMID 30999623, 2019). "The loss of PDG-1b contributes to decreased respiration in VHL-deficient renal carcinoma cells." (PMID 31711497, 2019). "Notably, HIF-2α silencing was capable of rescuing H19 transcript upon combined treatment in the HIF-2α+ VHL-deficient renal carcinomas cellular context." (PMID 31426484, 2019). "Here, we find that DNA repair genes involved in double-strand break repair by homologous recombination (HR) and in mismatch repair, which are down-regulated by hypoxic stress, are decreased in VHL-deficient renal cancer cells relative to wild type VHL-complemented cells." (PMID 29435132, 2018).